MPP1 (MAGUK p55 scaffold protein 1)
Description:
Essential regulator of neutrophil polarity. Regulates neutrophil polarization by regulating AKT1 phosphorylation through a mechanism that is independent of PIK3CG activity (By similarity).
Synonyms: DXS552E; EMP55; PEMP; AAG12; MRG1
Tractability: Small molecule: it has a binding pocket of medium quality. Antibody: UniProt places it where antibodies can reach, with high confidence; its Gene Ontology location is reachable by antibodies, with high confidence; the Human Protein Atlas places it where antibodies can reach. PROTAC: ubiquitination databases record sites on it; its protein half-life has been measured.
Gene: Protein-coding gene on chromosome X (154,778,684 to 154,821,039, reverse strand). Ensembl gene ENSG00000130830.
Subcellular location: Cell membrane; Cell projection, stereocilium
Subcellular location (Human Protein Atlas): Plasma membrane; Centriolar satellite
Pathways (Reactome):
Sensory Perception: Sensory processing of sound by outer hair cells of the cochlea
Gene Ontology:
Molecular function: protein binding; GMP kinase activity; signaling receptor binding
Biological process: regulation of neutrophil chemotaxis; response to fluid shear stress; signal transduction; GDP metabolic process; GMP metabolic process
Cellular component: membrane; plasma membrane; cell-cell junction; cortical cytoskeleton; cell periphery; stereocilium
Homologues: Orthologues: chimpanzee MPP1 (100% identical), macaque MPP1 (99% identical), rabbit MPP1 (97% identical), guinea pig MPP1 (95% identical), mouse Mpp1 (93% identical), dog MPP1 (92% identical), tropical clawed frog mpp1 (66% identical), zebrafish mpp1 (64% identical), Drosophila melanogaster CASK (51% identical), Caenorhabditis elegans lin-2 (49% identical), Drosophila melanogaster vari (35% identical), Drosophila melanogaster metro (32% identical), and 2 more. Paralogues in human: CASK (56% identical), PALS2 (41% identical), MPP2 (40% identical), MPP7 (34% identical), MPP3 (31% identical), MPP4 (30% identical), PALS1 (27% identical).
Diseases named in the same sentence as MPP1 in open-access papers:
MPP1 is named in the same sentence as 25 diseases in open-access papers, as found by Europe PMC text mining. Sharing a sentence is not in itself a finding about the gene and the disease. The quoted sentences say what the papers report.
breast carcinoma (1 paper, 2017). "Further in cancers that display increased expression of ABCC4 and MPP1 (e.g., breast cancer and medulloblastoma), our findings suggest that disrupting the interaction between MPP1 and ABCC4 can improve the cytotoxicity of conventional therapy against tumors." (PMID 29146910, 2017).
cerebral malaria (1 paper, 2018). A sequestration of Plasmodium falciparum in the brain, which can cause coma and/or seizures. "The five identified proteins (ANK1, CD14, CDK14, ELANE, MPP1) were found to be elevated in the febrile convulsion group compared to cerebral malaria." (PMID 30442134, 2018). "Erythrocyte plasma membrane proteins were here identified as being elevated in malaria cases compared to controls and in severe malaria compared to mild malaria (GYPC) or increased in febrile convulsions compared to cerebral malaria (ANK1, MPP1)." (PMID 30442134, 2018).
colon cancer (1 paper, 2024). "Of these, Mpp1 is associated with the cytoskeleton and cell proliferation, Prdx6 is associated with migration and invasion in colon cancer, and Epb4.2 predicts survival outcomes in pancreatic cancer." (PMID 38542101, 2024).
depression (1 paper, 2022). "As the hub genes in the PPI networks, the expression of Mpp1 and Pidd1 may provide diagnostic and therapeutic value for depression." (PMID 35771226, 2022). "Consequently, further study is needed to understand the underlying mechanism of these DEGs (including Eps8l1, Plcb2, Mpp1, Pidd1) in Asmt-related depression and exercise effects, thus provide new targets for the treatment of exercise for depression." (PMID 35771226, 2022).
erythroleukemia (1 paper, 2018). Acute erythroid leukemia characterised by the presence of at least 50% erythroid precursors and at least 20% myeloblasts in the bone marrow. "To assess the functional role of MPP1 in membrane dynamics, we used a stable, lentiviraly transduced, MPP1 knock-down human erythroleukemia cell line (MPP1 KnD) along with control cells: wild-type HEL (WT, control) and HEL transduced with scrambled shRNA (SC)." (PMID 29719614, 2018).
gastric ulcer (1 paper, 2018). An ulcerated lesion in the mucosal surface of the stomach.
multiple system atrophy (1 paper, 2023). Multiple system atrophy (MSA) is a neurodegenerative disorder characterized by autonomic failure (cardiovascular and/or urinary), parkinsonism, cerebellar impairment and corticospinal signs with a median survival of 6-9 years. "MPP1 mRNA level has been reported to be decreased in two atypical parkinsonian disorders (multiple system atrophy (MSA) and progressive supranuclear palsy (PSP)) and PD compared with healthy controls." (PMID 36672967, 2023).
myeloid leukemia (1 paper, 2017). A clonal proliferation of myeloid cells and their precursors in the bone marrow, peripheral blood, and spleen. "To determine whether endogenous ABCC4 and MPP1 directly interacted in AML cells, we performed co-immunoprecipitation experiments using MO7e cells, a myeloid leukemia cell line derived from a pediatric patient." (PMID 29146910, 2017).
neurofibromatosis type 2 (1 paper, 2023). "In the context of neurofibromatosis type 2, MPP1 can bind to the FERM structural domain of the NF2 protein, a tumor suppressor gene encoded by the NF2 gene, potentially leading to a tumor-suppressive effect." (PMID 38169731, 2023).
osteosarcoma (1 paper, 2023). A usually aggressive malignant bone-forming mesenchymal neoplasm, predominantly affecting adolescents and young adults. "Four gene expression signatures (PLEKHO2, GBP2, MPP1, and VSIG4) linked to osteosarcoma prognosis were identified within the TARGET-osteosarcoma cohort, categorizing patients into two subgroups." (PMID 38169731, 2023). "Although PLEKHO2, VSIG4, MPP1, and GBP2 have been implicated in the pathogenesis of several cancers, their roles in osteosarcoma have not been reported to date." (PMID 38169731, 2023). "Finally, we focused on investigating the role of GBP2 in osteosarcoma and did not extensively explore the functions of PLEKHO2, VSIG4, and MPP1." (PMID 38169731, 2023).
cancer (9 papers, 2015 to 2023). A tumor composed of atypical neoplastic, often pleomorphic cells that invade other tissues. "Understanding the link between MPP1 and activation of H-Ras, may provide an important insight into the complexity of Ras related signaling pathways which may become a potential target for associated cancer therapies." (PMID 29719614, 2018). "The three prognostic markers (PAPSS2, ANGEL2, and MPP1) that hyper‐hydroxymethylated in CIN3 also play important roles in cancers." (PMID 34323415, 2021). "We demonstrate the link between MPP1-dependent PM dynamics and activation of PM-bound H-Ras, comprising a piece of the puzzle in the understanding of the complexity of membrane-associated signal-transduction pathways which could comprise a new target for future cancer therapies." (PMID 29719614, 2018). "Those 6 genes in the model (PDK4, MPP1, ASGR1, MS4A14, FCER1A and MX2), rarely reported in cancers, were found to be significantly related to the prognostic survival of KIRC patients." (PMID 34606472, 2021).
infection (2 papers, 2015 to 2022). The state of being infected such as from the introduction of a foreign agent such as serum, vaccine, antigenic substance or organism. "Infection alone produced an accumulation of MPP1, MPP2, MPP3, and MPP4 cells, and, as with HSCs, MPP1 and MPP2 cells accumulated to a lesser extent with infection plus imatinib compared to infection alone." (PMID 25822986, 2015). "At 30 days after infection, the CD45.1+ cell compartment showed no HSCs but a low number of MPP1 and myeloid-biased MPP3s in the BM." (PMID 35166205, 2022).
MPP1 also shares sentences with these, for which no sentence is quoted: leukemia (2 papers); Alzheimer disease (1); Cirrhosis (1); gastritis (1); gastrointestinal disease (1); malaria (1); medulloblastoma (1); pancreatic cancer (1); parkinsonian disorder (1); Parkinson’s (1); progressive supranuclear palsy (1); sarcoma (1); tumor (1).